TLR4 (toll like receptor 4)
Diseases named in the same sentence as TLR4 in open-access papers (continued):
Sharing a sentence is not in itself a finding about the gene and the disease.
Insulin resistance (continued). "This breakdown allows the transfer of LPS into the systemic circulation, activating TLR4 and beginning the cascade of pro-inflammatory signaling resulting in insulin resistance and metabolic inflammation." (PMID 41459531, 2025). "Toll-like receptor 4 (TLR4) significantly contributes to the onset of insulin resistance (IR) and inflammation, being expressed in insulin-responsive tissues." (PMID 40881124, 2025). "The gut microbiota–Toll-like receptor 4(TLR4)–nuclear factor kappa B(NF-κB) signaling is a key controller of low-grade chronic inflammation and insulin resistance in type 1 (T1DM) and type 2 diabetes mellitus (T2DM)." (PMID 41459531, 2025). "Its multi-faceted mechanisms—driving liver inflammation, insulin resistance, and fibrosis through the TLR4 signaling pathway—make it a valuable therapeutic target." (PMID 41190061, 2025). "The chronic low-grade inflammation and insulin resistance that characterize diabetes are also largely mediated by TLR4 signaling." (PMID 41002387, 2025). "B. vulgatus and E. coli promote hepatic fat accumulation and exacerbate insulin resistance by producing lipopolysaccharides (LPS), which activates the Toll-like receptor 4 (TLR4) pathway in the liver and nuclear factor kappa B (NF-κB) signaling pathways." (PMID 39664063, 2024). "Numerous studies have provided evidence to support the idea that Toll-like receptor 4 (TLR4) serves as a connection point between innate immunity and the development of insulin resistance induced by fatty acids." (PMID 39606781, 2024). "The findings suggest that 6-OHDA induces neurodegeneration via activation of TLR4 and GSK3β, indicating insulin resistance, and that insulin can improve these impairments." (PMID 39830652, 2024). "The present study evaluated the effect of insulin, an insulin receptor antagonist, and a TLR4 inhibitor on behavioral deficits and insulin resistance induced by 6-hydroxydopamine (6-OHDA)." (PMID 39830652, 2024). "TLR-4 downregulation in hepatocytes has been identified to resolve liver inflammation, improve insulin resistance, and reduce fat concentration in the liver." (PMID 38612504, 2024). "Mechanistically, BA mitigated inflammation and insulin resistance in GDM mice by inhibiting activation of the TLR4/NF-κB signaling pathway." (PMID 39429784, 2024). "Lastly, it is important to note that Toll-like receptor 4 (TLR4) in hematopoietic cells plays a critical role in the development of insulin resistance in adipose tissue." (PMID 39606781, 2024). "Endogenous lipids activate toll like receptor 4 (TLR4) that mediate both inflammation and insulin resistance in adipose tissue with paralleled activation of NF-κB." (PMID 38775851, 2024). "They showed that central resistin through TLR4 and activating the proinflammatory pathways induces insulin resistance." (PMID 38164476, 2024). "Signaling through Tlr3 and Tlr4, which lie upstream of Irf3, induced insulin resistance in murine adipocytes, while Irf3 knockdown prevented insulin resistance." (PMID 39683552, 2024). "Prior studies have proved that TMBIM1 promoted lysosomal degradation of TLR4 and inhibited high-fat diet-induced insulin resistance, hepatic steatosis, and inflammation." (PMID 37156795, 2023). "To investigate the sufficiency of hepatocyte TLR4 in alcohol-induced insulin resistance, we used a mouse model that is conditionally null for TLR4 (Tlr4LoxTB)." (PMID 36979389, 2023). "Other studies also demonstrated that SFAs indeed can activate Toll-like receptor 4-(TLR4-) and TLR2-mediated pro-inflammatory signaling pathways and consequently increase the risk of insulin resistance." (PMID 37901107, 2023). "Increased TLR4 protein expression has been reported in the SkM of subjects with obesity and T2DM, which in turn was associated with insulin resistance." (PMID 37435031, 2023).
Insulin resistance (continued). "Fenofibrate improved both HFD-induced insulin resistance in skeletal muscle and palmitic acid-induced insulin resistance in myotube cells, thus reduced ER stress-induced inflammation via inhibiting TLR4/NF-κB pathway." (PMID 36724021, 2023). "Increased HMGB1 can increase TLR4 and RAGE, enhance the activity of the autophagy signaling pathway, and lead to dysregulated autophagy, thus causing insulin resistance, systemic inflammatory response, and organ dysfunction." (PMID 37065747, 2023). "For ITTs, Tlr4LoxTB mice maintained similar blood glucose levels on both control and alcohol-containing diets, suggesting that whole-body TLR4 knockout mice were resistant to alcohol-induced systemic insulin resistance." (PMID 36979389, 2023). "Collectively, these findings indicate that hepatocyte TLR4 plays a role in regulating alcohol-induced insulin resistance in mice." (PMID 36979389, 2023). "It was found that an increase in ceramide is required for TLR4-dependent insulin resistance in an obese mouse model, and with parallel decreases in sphingosine-1-phosphate, this has been shown to increase apoptosis." (PMID 37764683, 2023). "For example, hepatocyte-derived EVs enriched with saturated fatty acids activate TLR4 signaling, promoting pro-inflammatory responses and hepatocyte insulin resistance." (PMID 37896221, 2023). "In summary, these findings provide in vivo evidence that hepatocyte TLR4 is a significant contributor to the development of excessive alcohol intake-induced insulin resistance." (PMID 36979389, 2023). "Meanwhile, DOP decreased the level of LPS and inhibited the expression of TLR4 by regulating the composition of the gut microbiota, consequently relieving the inflammation and alleviating insulin resistance." (PMID 37372523, 2023). "The presence of LPS in the Bacteroides cell wall, by binding to toll-like receptor 4 (TLR4), can also alter signaling pathways and eventually lead to insulin resistance." (PMID 37515062, 2023). "Other studies found that anthocyanins reduced insulin resistance by inhibiting hepatic inflammation through the reduction of TLR4/NF-κB/JNK in liver tissues and improving oxidative stress." (PMID 37799768, 2023). "We found that hepatocyte TLR4 is required in mediating insulin resistance following excessive alcohol intake." (PMID 36979389, 2023). "Another key actor in the development of both inflammation and insulin resistance is TLR4, which is expressed in insulin target tissues." (PMID 37371102, 2023). "Fetuin-A is also an endogenous ligand for toll-like receptor 4 (TLR4), enabling saturated free fatty acids to induce insulin resistance through activation of TLR4 signaling." (PMID 37367914, 2023). "Collectively, these findings suggest that hepatocyte TLR4 is both required and sufficient in the development of insulin resistance induced by alcohol overconsumption." (PMID 36979389, 2023). "In general, studies have shown a protective effect of TLR4 inhibition against lipid-induced insulin resistance in skeletal muscle." (PMID 36066991, 2022). "Serum lipids and free fatty acids can induce insulin resistance and impaired glucose metabolism, and can also activate inflammatory pathways in innate immune cells via TLR4 recognition of these lipids." (PMID 35812447, 2022). "Preclinical studies have established TLR4 as an important mechanistic link between chronic low-grade inflammation and insulin resistance." (PMID 36066991, 2022). "We also reported that ProT participates in the induction of insulin resistance through the Toll-like receptor 4 (TLR4)-NF-κB-dependent signaling pathway." (PMID 36471329, 2022). "In this study, we examined the effects of a selective TLR4 antagonist to further evaluate the role of TLR4 in the etiology of insulin resistance in humans." (PMID 36066991, 2022). "TLR4 knockout mice have been reported to protect against insulin resistance induced by high fat diet (HFD)." (PMID 35769384, 2022).
Insulin resistance (continued). "Patients with insulin resistance have high levels of plasma free fatty acids (FFAs), which are ligands of the TLR4 pathway." (PMID 35088922, 2022). "Binding of lipopolysaccharide to the complex of CD14 and toll-like receptor 4 on the surface of innate immune cells, LPS can induce systemic inflammation, which ultimately impairs insulin sensitivity and induces insulin resistance-related metabolic disorders." (PMID 36093200, 2022). "One-way chronic inflammation can be explained in patients suffering from insulin resistance is by the activation of the innate immune signaling pathway triggered by toll-like receptor 4 (TLR4)." (PMID 35401518, 2022). "Studies in cell cultures and rodents suggest that TLR4 is involved in the pathogenesis of insulin resistance, but direct data in humans are limited." (PMID 36066991, 2022). "Insulin resistance is established to correlate with elevated free fatty acids (FFAs) in the plasma, as FFAs induce inflammation involving TLR4/NF-κB signalling." (PMID 36009315, 2022). "In this way, FFA disrupts insulin signaling through toll-like receptor 4 (TLR4) pathway, resulting in insulin resistance (IR)." (PMID 35190756, 2022). "Future studies with a larger sample would be helpful to further delineate the role of TLR4 in human insulin resistance." (PMID 36066991, 2022). "The mechanism through which TLR4 leads to a state of insulin resistance is through increased ceramide synthesis via IKKβ and NF-κB." (PMID 36499769, 2022). "TLRs, particularly TLR2 and TLR4, are involved in the development and progression of insulin resistance and diabetic complications such as diabetic nephropathy and vascular damage." (PMID 36589440, 2022). "Here, we used eritoran to investigate the role of TLR4 in insulin resistance and confirmed that it was a potent TLR4 inhibitor in peripheral blood from the research participants who received the drug." (PMID 36066991, 2022). "Previous studies have demonstrated that TLR4 can be involved in hyperinsulinemia, insulin resistance, lipid metabolism disorder, endothelial cell dysfunction, and blood coagulation." (PMID 36148071, 2022). "Luteolin has an obvious hypoglycemic effect, improving insulin resistance in DM rats by downing the expression of TLR4, JUK mRNA, and protein levels." (PMID 36452059, 2022). "In turn, FetA acts as an endogenous ligand of TLR4 to promote lipid-induced insulin resistance in adipocytes." (PMID 35909571, 2022). "On the one hand, fetuin-A acts as an endogenous ligand for the TLR4, which enables free fatty acids to activate TLR4-signaling to induce insulin resistance, and stimulates production of pro-inflammatory cytokines from adipocytes and macrophages." (PMID 34998417, 2022). "Through binding of the ligands (e.g., PAMPs and DAMPs), TLR4 contributes to the development of insulin resistance and inflammation." (PMID 33478014, 2021). "Activation of TLR4 has been found to promote insulin resistance in DM and participate in its complications such as diabetic nephropathy, diabetic retinopathy, and diabetic vascular disease." (PMID 35153741, 2021). "The importance of the TLR-4 pathways in worsening metabolic disease was confirmed by inducing a deletion of TLR-4 which subsequently prevented high fat diet (HFD) induced insulin resistance." (PMID 34900829, 2021). "A recent study also reported that irisin alleviates lipotoxicity-induced β-cell insulin resistance and inflammatory response through inhibition of TLR4/NF-kB pathways." (PMID 34943814, 2021). "TLR4, expressed in insulin target tissues, plays a crucial role in the development of insulin resistance and inflammation." (PMID 34445300, 2021). "IL6 also contributes to insulin resistance by inducing TLR4 expression in skeletal muscle via STAT376." (PMID 33820928, 2021). "Dietary fatty acids and LPS have been shown to promote insulin resistance through the activation of TLR4." (PMID 34682732, 2021).
Insulin resistance (continued). "Once activated, this TLR4 pathway will aggravate insulin resistance and participate to NAFLD progression." (PMID 34650994, 2021). "Recently, TLR4 has grabbed much attention due to its role in the progression of diabetes type 2, insulin resistance, in addition to its profound contribution in damaging beta cells in the pancreas." (PMID 34912223, 2021). "TLR4 is known to trigger lipase activity and insulin resistance in adipocytes and breakdown of myofiber proteins in muscle." (PMID 34637789, 2021). "The present study focused on exploring the relationship of TLR4 with cardiovascular injury during aging using TLR4−/− aged mice and analyzing the effects of TLR4 knockout on insulin resistance, inflammation, and oxidative stress in aged mice." (PMID 34740366, 2021). "The results indicate that WISP-1 promotes insulin resistance through the Toll-like receptor 4 (TLR-4)-mediated and c-Jun N-terminal kinase (JNK)-dependent pathway." (PMID 33498604, 2021). "Recently, fetuin-A was found to act as an endogenous ligand for TLR4 to promote free fatty acid-induced insulin resistance, in the adipose tissue." (PMID 34566972, 2021). "Recent studies indicate that cows with high body condition scores exhibit insulin resistance and a proinflammatory state in the liver and that TLR4 plays an important role in insulin resistance." (PMID 34966805, 2021). "RP105 KO and MD-1 KO mice had lesser HFD-induced adipose tissue inflammation and insulin resistance compared to TLR4 KO and wildtype mice." (PMID 34414191, 2021). "The gut TLR4, a receptor for LPS, can influence the TJ function and activates signaling pathways leading to diet-induced insulin resistance and atherosclerosis." (PMID 35052763, 2021). "CD14/TLR4 plays a vital role in the recognition of bacterial origin LPS and induces cascade response of inflammation reaction, which leads to insulin resistance." (PMID 34966475, 2021). "In the insulin resistance state, macrophages are activated by the recognition of free fatty acids from hypertrophied adipocytes or LPS through the TLR4/MD-2 complex to induce TNF-α production." (PMID 34414191, 2021). "Many studies have shown that the LPS/TLR4 signaling pathway mediates inflammation, oxidative stress, insulin resistance and liver fibrosis, and is one of the key factors in the pathology of NAFLD." (PMID 34945677, 2021). "The levels of pro-inflammatory cytokines (TNF-α, IL-1β and IL-6) and the expression of TLR4 were downregulated (P < 0.05), while the insulin resistance index, HOMA-IR showed improvement by GP treatment (P < 0.05)." (PMID 32024509, 2020). "It was shown that activation of TLR4/IRF3 signaling pathways results in insulin resistance in murine adipocytes." (PMID 33050324, 2020). "High levels of circulating LPS stimulates Toll-like receptor 4 (TLR4) signaling in various cells and leads to metabolic inflammation and insulin resistance in obese mice." (PMID 33408699, 2020). "HFD activates several proinflammatory signaling pathways, and NF-κB signaling is a crucial pathway in this process, which is the downstream of TLR4 and leads to the development of insulin resistance, cytokine production, and eventually immune cell recruitment." (PMID 33162789, 2020). "Accordingly, it was demonstrated that deletion of the TLR4 gene protects mice from diet-induced insulin resistance, despite an increase in weight gain compared to the control." (PMID 32947825, 2020). "In particular, TLR4 is an important mediator of insulin resistance and hepatic inflammatory pathways." (PMID 32182914, 2020). "It has been proposed that the sphingolipid ceramide is also an important effector of insulin resistance through a signaling network linking lipid-induced inflammatory exacerbation to TLR-4 activation." (PMID 33042016, 2020).
Insulin resistance (continued). "As TLR4 is connected to insulin metabolism via cytokine signaling, activation of TLR4 links LPS to insulin resistance presumably by altering insulin receptor signaling in the presence of inflammatory cytokines, as explained in more detail in Section 2.5.2." (PMID 32218248, 2020). "Circulating LPS binds to Toll-like receptor 4 (TLR-4), and then activates the inflammatory pathway and leads to insulin resistance." (PMID 31952248, 2020). "LPS can modulate the signaling pathways of TLR4, which is related to the production of proinflammatory cytokines and insulin resistance (22, –, 24)." (PMID 32265324, 2020). "Intervention of the TLR4 expression regulates macrophage polarization and metabolic inflammation and further alleviates insulin resistance and lipid deposition in hepatocytes." (PMID 33013197, 2020). "TLR-4 dependent insulin resistance is activated by elevated endogenous and exogenous ligands such as FFAs and enteric lipopolysaccharides." (PMID 33042016, 2020). "TLR4 knockout mice challenged with a HFD develop less insulin resistance and have a better glucose tolerance test than their wild-type litter mates." (PMID 33505393, 2020). "With respect to inflammation, TLR4 and TLR2 activation by saturated FFA also causes insulin resistance, potentially via JNK in skeletal muscle." (PMID 32183037, 2020). "Mouse models have shown the importance of TLR4 and its signaling in diet-induced insulin resistance and atherosclerosis." (PMID 33505393, 2020). "Saturated FAs activate TLR4 receptors and potentiate inflammation and insulin resistance in adipocytes via the TLR4/PI3K/PKB signaling pathway." (PMID 32878255, 2020). "Periodontal pathogenic substances such as LPS promote the development of insulin resistance (IR) through toll like receptor-4 (TLR-4) signaling in the liver." (PMID 32411181, 2020). "In this study, we found that lentiviral-packaged TLR4-siRNA inhibited the expression of TLR4 in the liver and significantly improved metabolic inflammation and insulin resistance induced by high-fat diet." (PMID 33013197, 2020). "In such a scenario, TLR4 seems to be the connection hub among the consumption of dietary fats, metabolic inflammation, and insulin resistance." (PMID 32414055, 2020). "Although its precise mechanisms remain obscure, it is generally agreed upon that its expression is induced by proinflammatory stimuli and that it in turn perpetuates the proinflammatory response and insulin resistance by interacting with TLR4." (PMID 32604889, 2020). "Intervention of the TLR4 expression in macrophages regulates macrophage polarization and metabolic inflammation and herein alleviates insulin resistance and lipid deposition in hepatocytes." (PMID 33013197, 2020). "Studies in both animals and humans showed that high levels of circulating FFA can lead to peripheral insulin resistance as well as stimulate cytokine production of macrophages and act as ligands for the toll-like receptor 4 (TLR4) complex." (PMID 33322742, 2020). "TLR4 responds to the high circulating level of fatty acids and induces inflammatory signaling, which leads to insulin resistance." (PMID 31974095, 2020). "Toll-like receptor 4 (TLR4) is a modulator of innate immunity that contributes to both insulin resistance and OA pathogenesis." (PMID 31781260, 2019). "TLR4 expression is increased in obese mice and humans and positively correlates with insulin resistance." (PMID 30906281, 2019). "This translocation of LPS into the plasma leads to binding of LPS to TLR4, which will induce the activation of the NF-κB pathway in different tissues, which results in systemic inflammation and insulin resistance." (PMID 30832230, 2019). "The process involves Fetuin A serving as an endogenous ligand for the Toll-like receptor (TLR) 4, which then enables free fatty acids to activate TLR4 signaling to induce insulin resistance." (PMID 31736870, 2019).